SHBG (sex hormone binding globulin)
Diseases named in the same sentence as SHBG in open-access papers (continued):
Sharing a sentence is not in itself a finding about the gene and the disease.
acne (48 papers, 2011 to 2025). An inflammatory process of the sebaceous glands which is characterized by comedones, nodules, papules and/or pustules on the skin. "A low SHBG level may be only abnormal biochemical test in teenage girls presenting with menstrual irregularity and acne, who may later develop one or other of the diagnostic phenotypes of PCOS." (PMID 33139661, 2020). "Therapies aimed at reducing androgen production or increasing SHBG can help decrease sebum production and acne severity." (PMID 40337376, 2025). "Increased levels of insulin also stimulate androgen production and can reduce serum levels of sex hormone-binding globulin (SHBG), consequently strongly enhancing androgen activity and favoring acne development." (PMID 38398863, 2024). "The levels of androgens (such as testosterone), IGF-1, sex hormone-binding globulin (SHBG), and other important hormones in acne patients are measured and analysed using hormonal assays." (PMID 38384651, 2024). "On the contrary, these authors found lower free testosterone index values and higher SHBG levels in women with higher acne severity." (PMID 36552842, 2022). "In our study, we also found that the SHBG values were significantly lower in acne patients compared to the control group." (PMID 36552842, 2022). "The results of our study also provide an explanation that the therapeutic effect of oral contraceptives on acne is realized, among other things, by increasing the SHBG production in the liver, thereby reducing the bioavailability of active testosterone." (PMID 36552842, 2022). "In one study, the serum sex hormone binding globulin (SHBG) values correlated negatively with acne severity, possibly due to an increased level of free testosterone." (PMID 32586344, 2020). "NOMAC/E2 exhibits a neutral to slightly positive effect on acne, which is consistent with its moderate effect on sex hormone-binding globulin (SHBG) and androgen levels." (PMID 21995590, 2011). "However, it is well-known that estrogens suppress sebum production and decrease acne lesions by increasing sex hormone-binding globulin and thereby decrease the amount of circulating free testosterone." (PMID 40132142, 2025). "High levels of omega-3 fatty acids found in fish and the high fiber content in fruits and vegetables may reduce acne risk by decreasing the Insulin-like growth factor 1 (IGF-1) level and increasing sex hormone-binding globulin (SHBG) level." (PMID 34133464, 2021). "As in the case described, a low plasma SHBG is often the only abnormal parameter of the androgen panel tests in teenage girls with menstrual irregularity and acne; SHBG reduction may be an early manifestation of PCOS, prior to an overt phenotype emerging." (PMID 33139661, 2020). "Co-supplementation did not affect serum SHBG and plasma NO levels, as well as acne and alopecia." (PMID 30665436, 2019).
Hypertension (39 papers, 2013 to 2026). The presence of chronic increased pressure in the systemic arterial system. "Subgroup analyses were conducted to explore the association between testosterone, SHBG, and RA across different demographic and clinical subgroups, including age, race/ethnicity, BMI, hypertension, and PIR." (PMID 39759528, 2024). "The aim of this study was to investigate the association of sex hormone-binding globulin (SHBG) and hypertension in a Swedish population." (PMID 23594436, 2013). "We did not found studies comparing the strength of the association between SHBG and hypertension with other risk factors for hypertension." (PMID 23594436, 2013). "They reported an association between hypertension and low concentrations of SHBG in women in the crude analysis." (PMID 23594436, 2013). "As the association between SHBG and hypertension in women was stronger over the age of 50 we suppose that these gender differences can at least in part be addressed to the menopause." (PMID 23594436, 2013). "It should also be emphasized that as this is a cross-sectional study the causality between SHBG and hypertension cannot be established and it is possible that hypertension or associated factors lead to decreased concentrations of sex hormone-binding globulin." (PMID 23594436, 2013). "An inverse association was observed between SHBG and hypertension in both men (B=−0.024 p<0.001) and women (B=−0.022 p<0.001)." (PMID 23594436, 2013). "The purpose of this study was therefore to investigate the association between hypertension and SHBG, in both men and women in a Swedish population." (PMID 23594436, 2013). "It must be emphasized that in a minor study with men with hypertension it was found a strong association between SHBG and renin that can be another pathway for direct effects of SHBG on the control of blood pressure." (PMID 23594436, 2013). "There are some publications concerning the association between hypertension and SHBG in men, but very few in women." (PMID 23594436, 2013). "A mendelian randomization found that sex hormone-binding globulin, testosterone and oestradiol may causally affect risk of hypertension and coronary atherosclerotic outcomes." (PMID 38375191, 2024). "A cross-sectional study in men conducted in Tromsö, which aimed to investigate the association between testosterone on one hand and hypertension and left ventricular hypertrophy on the other hand, found an age-independent association between SHBG and both systolic and diastolic blood pressure." (PMID 23594436, 2013). "However, only a few studies have presented information about the association between SHBG and hypertension." (PMID 23594436, 2013). "In men, an association between quartiles of SHBG and hypertension (OR=2.2 p=0.007) was found." (PMID 23594436, 2013). "The exceptions are an increased risk of hypertension and cardiovascular disease, both of whose regression equations account for >20% of the cohort variance, and which already include contributions from T and SHBG (negatively), and age, LH, and BMI (positively)." (PMID 36425465, 2022). "The results revealed causality between SHBG levels and reduced risk of CHD, myocardial infarction, as well as hypertension." (PMID 38796576, 2024). "Interaction analysis revealed significant interactions between testosterone, SHBG, and RA for age, race/ethnicity, hypertension, and PIR (p for interaction < 0.05)." (PMID 39759528, 2024). "High serum SHBG levels are causally associated with reduced risk of CHD, MI, and hypertension, in which the improvement of lipid profile largely mediates the causal effect of CHD risk reduction." (PMID 38796576, 2024). "Serum SHBG levels are lower in women with gestational diabetes and have demonstrated predictive value for gestational diabetes and hypertension." (PMID 37573326, 2023).
Hypertension (continued). "The outcomes of the multivariate binary logistic regression models analysis suggest that advanced age, hypertension, hyperuricemia, hypertriglyceridemia, and FSH were risk factors, while high values of LH, TT, and SHBG were protective factors for MAFLD." (PMID 34706716, 2021). "Reports from the multiethnic study of atherosclerosis showed that hypertension events were positively correlated with testosterone and estradiol levels and negatively correlated with sex hormone binding globulin levels." (PMID 31341663, 2019). "After adjusting for age, the indicators (central obesity, hypertension, fasting insulin, SHBG, dyslipinaemia) for metabolic disturbances were significantly higher in PCOS than in non-PCOS groups." (PMID 25223276, 2014). "In order to compare the SHBG with other conventional risk factors for hypertension, we standardized age, BMI, HOMA-IR and SHBG." (PMID 23594436, 2013). "In contrary in women the decrease in SHBG were firstly observed when they had developed hypertension." (PMID 23594436, 2013). "In men, SHBG decreased significantly with the severity of high blood pressure." (PMID 23594436, 2013). "Additionally, we found a nonlinear relationship between both testosterone and SHBG with RA risk, which was further influenced by factors such as age, race/ethnicity, hypertension, and PIR." (PMID 39759528, 2024). "Neither was the association between SHBG and hypertension in males at baseline reported." (PMID 23594436, 2013). "Thus, it appears that while BMI and hypertension did not mediate our associations, SHBG could be a mediator." (PMID 40564988, 2025). "Furthermore, hypertension-induced vascular damage and metabolic dysregulation could amplify immune activation, creating a feedback loop that reinforces RA severity in individuals with low testosterone and elevated SHBG levels." (PMID 39759528, 2024). "Following further adjustment for hypertension, T2D, HDL, and triglycerides in model 2, only lower SHBG levels [T3 versus T1: OR= 0.46 (0.30–0.71), p trend = 0.0012] were significantly associated with NAFLD." (PMID 35741728, 2022). "This MR study demonstrates negative causality between genetically predicted serum SHBG levels and the risk of CHD, MI, as well as hypertension." (PMID 38796576, 2024). "The IVW method indicates that each increase of one-standard-deviation (1-SD) in SHBG is associated with a reduced risk of CHD (OR 0.73; 95% CI 0.63–0.86), MI (OR 0.77; 95% CI 0.66–0.90), and hypertension (OR 0.84; 95% CI 0.74–0.96), but not with the other two CVDs." (PMID 38796576, 2024).
Abdominal obesity (36 papers, 2012 to 2026). Excessive fat around the stomach and abdomen. "In women, SHBG mediated 14.7% and 20.0% of the associations between general and abdominal obesity and cholecystectomy, respectively, whereas testosterone mediated smaller proportions (2.7% and 1.8%)." (PMID 41872976, 2026). "After considering the interaction between central obesity and SHBG levels, the significant association was evident only in obese women (P for interaction = 0.025)." (PMID 29213285, 2017). "The aim of this study was to determine the relationship between SHBG and arterial stiffness in association with central obesity in women." (PMID 29213285, 2017). "Apart from hypertriglyceridemia and abdominal obesity, SHBG and FT were also strongly associated with hyperglycaemia." (PMID 25019163, 2014). "In conclusion, we observed a robust, dose-response relationship of low testosterone and SHBG concentrations with prevalent and incident MetS in men, with associations being primarily mediated through abdominal obesity, hypertriglyceridemia and hyperglycaemia." (PMID 25019163, 2014). "However, on further adjustments for both SHBG and waist circumference, the significant difference disappeared, thus suggesting a role for abdominal obesity in the association of testosterone with both MetS and type 2 DM." (PMID 30057912, 2018). "Thus, central obesity may be a confounding factor for the relationship between SHBG levels and cardiovascular risk." (PMID 29213285, 2017). "This process could be exacerbated by changes in sex-hormone levels (as observed in our study), such as relative hyperestrogenism, decreases in SHBG levels, and androgen deficiency—that is, medical conditions commonly associated with MetS, and in particular with abdominal obesity." (PMID 26516352, 2015). "Obesity can intensify the hyperandrogenic state in PCOS because abdominal obesity alters fat-soluble androgen clearance and deposition and also exacerbates hyperandrogenism by reduction of SHBG levels." (PMID 32133054, 2019). "Abdominal obesity is associated with dysregulation of sex steroid levels in PCOS, such as androgen overproduction and reduction of sex hormone-binding globulin (SHBG)." (PMID 32133054, 2019). "Taken together these data suggest low SHBG is a marker of abdominal obesity and increased serum triglycerides, conditions which are known to have been associated with low testosterone and low T4." (PMID 29995902, 2018). "When interaction terms between central obesity and SHBG levels were considered, significant correlation was observed only for the centrally obese group." (PMID 29213285, 2017). "After considering the interaction term between SHBG levels and central obesity, SHBG levels were found to be negatively correlated with PWV only in the obese group; the interaction was significant (P for interaction = 0.025)." (PMID 29213285, 2017). "Women with central obesity usually have lower serum SHBG concentrations in comparison with their age- and weight-matched counterparts with peripheral obesity." (PMID 28620242, 2017). "Using multivariate logistic regression, central obesity and FAI were risk factors, while SHBG was a protective factor on the occurrence of Mets and IR in PCOS women (OR: 1.132, 1.105 and 0.995)." (PMID 25223276, 2014). "Our results were in agreement with previous reports that low SHBG levels correlated with abdominal obesity in postmenopausal women." (PMID 23484029, 2013). "Similarly, girls with congenital adrenal hyperplasia exhibit reduced SHBG levels, possibly due to central obesity and IR." (PMID 40863113, 2025). "At the same time, abdominal obesity is associated with several hormonal imbalances, including leptin, insulin-like growth factor (IGF-1), and abnormalities in sex hormone binding globulin (SHBG)." (PMID 40129671, 2025).
Abdominal obesity (continued). "The use of OCP [OR = 0.66; 95% CI: 0.54,0.80] was associated with lower odds of central obesity and every 1-unit increase in log-transformed SHBG (LSHBG) concentrations [β = −0.96; OR = 0.32; 95% CI: 0.24,0.42] was significantly associated with a lower likelihood of central obesity." (PMID 40308359, 2025). "The drop in SHBG concentration increases testosterone levels, which may further increase abdominal obesity and inflammation, therefore creating a vicious cycle." (PMID 34501389, 2021). "Furthermore, abdominal obesity induces ovarian and adrenal androgen production, whereas sex hormone binding globulin (SHBG) level is decreased." (PMID 34501389, 2021). "Thus, since SHBG concentration is a putative biomarker of abdominal obesity-related MS, we investigated the impact of AE and BE interventions on serum SHBG levels." (PMID 33664334, 2021). "Central obesity has been thought to be a major determinant of SHBG levels." (PMID 29213285, 2017). "Central obesity was significantly and inversely correlated to serum TT and SHBG." (PMID 27711240, 2016). "Associations of testosterone and SHBG with MetS were strongest in non-overweight men and abdominal obesity, hypertriglyceridemia and hyperglycaemia were the main drivers of the overall associations found." (PMID 25019163, 2014). "As expected, differences in SHBG levels between PCOS women and controls were due to body weight and abdominal obesity." (PMID 30850700, 2019). "Extracellular SHBG prove to be a determinant of cardiometabolic disorders, independent of abdominal obesity and IR." (PMID 39411775, 2024). "Regardless of BMI value, a negative connection exists between central obesity and testosterone or SHBG concentrations." (PMID 37563562, 2023).
depression (34 papers, 2015 to 2025). "In PheWAS, subtype 5 was positively associated with hair balding patterns, alcohol and cigarette consumptions, blood pressure, testosterone levels, risk-taking, and cannabis use, while it was negatively associated with SHBG levels and depression symptoms." (PMID 40766217, 2025). "Considering the potential impact of RA, IBD, SHBG, asthma, depression, NAFLD, and PBC on OP risk, we suggest promoting increased physical activity, establishing regular lifestyle habits, and enhancing disease prevention awareness." (PMID 39886030, 2024). "In conclusion, this study suggests that RA, IBD, CD, NAFLD, PBC, asthma, depression, and SHBG are identified as risk factors for OP, while BMR and GM are considered protective factors." (PMID 39886030, 2024). "A greater risk of depressive symptoms was positively associated with SHBG in a study of depressive disorders in post-menopausal women." (PMID 35444632, 2022). "Results of the Mendelian randomization analysis of predictors of testosterone from the SHBG region showed that genetically predicted testosterone was positively associated with depression and RA, while negatively associated with T2D." (PMID 32610558, 2020). "Interestingly, one Mendelian randomization study found a significant positive correlation between SHBG and risk of depression only in females, underlying its possible specific role in estrogen-related mood episodes." (PMID 39766785, 2024). "SHBG was positively and statistically associated with depression risk (p = 0.003) in all women." (PMID 35444632, 2022). "Similarly, one unit increase in log transformed testosterone using variants from the SHBG locus was associated with depression (OR = 1.02, p = 0.001), RA (OR = 1.32, p < 0.001) and T2D (OR = 0.88, p = 0.003)." (PMID 32610558, 2020). "In this study, plasma SHBG, which has been previously linked to depression, showed the sharpest difference over time between responders and non-responders (adjusted p-value = 2.70 × 10-3), decreasing gradually with time in responders and increasing gradually with time in non-responders." (PMID 33126421, 2020). "Limitations include the cross-sectional design, single-center setting, reliance on total rather than free testosterone, and the possibility of residual confounding from unmeasured factors such as depression, medication use, or SHBG levels." (PMID 41170246, 2025). "With respect to PheWAS, our results showed that subtype 4 was associated with lower blood testosterone levels and no hair balding patterns, as well as higher level of sex hormone-binding globulin (SHBG) and depression symptoms." (PMID 40766217, 2025). "Depression scores increased with higher levels of SHBG (coef = 0.2398; p = 0.002) and similarly with DHEA-S (coef = 0.0867; p = 0.011)." (PMID 39233885, 2024). "The result remained true for the relationship between SHBG and depression and all weight median MR analyses." (PMID 33802106, 2021). "For depression-like behaviors, SHBG, FAI, age, WC, WHR, number of deliveries, fasting insulin, FPG, and HOMA-IR were significant risk factors with odds ratios of 0.203, 1.268, 1.639, −0.403, 46.293, −4.199, −2.805, −11.709, and 10.749, respectively (P < 0.05)." (PMID 34744814, 2021). "Also, SHBG, which is correlated with T, was significantly lower in the atypical depression subtype compared with the melancholic subtype." (PMID 25999864, 2015). "Furthermore, another Mendelian randomization study demonstrated that SHBG had a negative causal association with major depression in males, which was supported by our observation of a negative Bonferroni-significant genetic correlation between the two." (PMID 40727568, 2025). "None of the androgens or SHBG were significantly associated with severity of depression." (PMID 33579903, 2021).
depression (continued). "Through MR analysis, UVMR results showed a causal relationship between smoking, time spent using computer, time spent on TV, sitting height, BFP, major depression, BMI, HDL, SHBG and cervical spondylosis in 26 candidate mediators." (PMID 38725482, 2024). "In summary, the College-based LMP showed positive effects of improvement in variables of partial domain of PMS (depression and anxiety) and sleep duration, but did not render the MCI, SHBG, T, and FAI." (PMID 33396852, 2020).